MIR100HG (mir-100-let-7a-2-mir-125b-1 cluster host gene)
Diseases named in the same sentence as MIR100HG in open-access papers (continued):
Sharing a sentence is not in itself a finding about the gene and the disease.
cancer (24 papers, 2018 to 2025). A tumor composed of atypical neoplastic, often pleomorphic cells that invade other tissues. "Dysregulation of MIR100HG has been detected in a diversity of cancers in association with clinical outcomes." (PMID 37487022, 2023). "The errant expression of MIR100HG has inspired people to investigate the function of MIR100HG and its diagnostic and therapeutic potential in cancers." (PMID 36212400, 2022). "It is possible that the dual action of MIR100HG in cancer is linked to the dual action of TGFβ, known to have antitumor properties in certain cancers and protumorigenic actions in others, a matter worth examining in future studies." (PMID 33941855, 2021). "With further research in the future, Mir100hg may become a new diagnostic marker and clinical therapeutic target for cancer." (PMID 37735657, 2023). "LncRNA MIR100HG was dysregulated in many cancers and played distinctively complex and contradictory roles, which involved tumorigenesis, proliferation, and invasion or inhibition of these biological behaviors of tumors." (PMID 36911392, 2023). "MIR100HG is a miRNA host gene whose roles in the development of diverse disorders, principally cancers, are being clarified." (PMID 37487022, 2023). "A study centered on understanding the impact of MIR100HG, a microRNA host gene situated on chromosome 11q24.1, investigated its role in metastasis and prognosis among individuals with cancer specifically CRC." (PMID 38042769, 2023). "Based on the Kaplan–Meier analyses, patients with this type of cancer and high levels of MIR100HG expression have poorer disease‐free and overall survival times compared with those having low levels of MIR100HG." (PMID 37487022, 2023). "MIR100HG, also known as lncRNA mir-100-let-7a-2-mir-125b-1 cluster host gene, is a new and critical regulator in cancers in recent years." (PMID 36212400, 2022). "In this review, we will highlight the characteristics, mechanisms, pathways, chemoresistance, and current research progress of MIR100HG in expression patterns, functions, and clinicopathological characteristics of cancers." (PMID 36212400, 2022). "The expression pattern, functions, and clinicopathological characteristics of MIR100HG in diverse cancers have been summarized." (PMID 36212400, 2022). "The physiological role of MIR100HG, the interaction between MIR100HG and the cancer microenvironment, and the function of MIR100HG in immune response, cell metabolism, starvation/autophagy, and neo-vascularization need to be investigated." (PMID 36212400, 2022). "While the regulatory mechanisms of MIR100HG in multiple cancers have been investigated, studies on MIR100HG remain in the primary stage, and many key issues need to be further addressed." (PMID 36212400, 2022). "Determining the independent roles that exist for host MIR100HG in different cancers is an open area of investigation." (PMID 36212400, 2022). "In this review, we will highlight the characteristics and introduce the role of MIR100HG in different cancers, and summarize the molecular mechanism, pathways, chemoresistance, and current research progress of MIR100HG in cancers." (PMID 36212400, 2022). "We then established a role of MIR100HG in TGFβ autoinduction, a central feature in TGFβ biology, especially in the context of cancer." (PMID 33941855, 2021). "We here establish that TGFβ upregulates spliced MIR100HG, which positively regulates TGFβ responses in several normal and cancer cell types." (PMID 33941855, 2021). "Our observations are compatible with recent findings that demonstrated a function of MIR100HG as a HuR protein facilitator, and extend this model in the context of TGFβ cancer biology." (PMID 33941855, 2021). "Wet-lab experiments are required to understand the molecular mechanism of MAGI2-AS3 and MIR100HG in these cancers." (PMID 34681112, 2021). "Since TGFβ induces MIR100HG, which enhances TGFβ signaling in normal and carcinoma cells, we examined MIR100HG expression in cancer patients." (PMID 33941855, 2021).
cancer (continued). "MIR100HG was previously reported to act as a regulator of hematopoiesis and oncogenes in many cancers." (PMID 30323832, 2018). "Sixteen lncRNAs were of unknown function, six were described in cancer, one connected with macrophages polarisation, and four were associated with CVDs, mainly with SMC function and phenotypic switch (NEAT1, MIR100HG, HIF1A-AS3, and MRI29B2CHG)." (PMID 38616192, 2024). "Dysregulation of MIR100HG has been detected in a diversity of cancers." (PMID 38612674, 2024). "MIR100HG expression has been found to be induced by TGFβ in different cancer types." (PMID 37487022, 2023). "Expression and function of MIR100HG in clinical samples from cancer patients." (PMID 37487022, 2023). "MIR100HG is also involved in the induction of chemoresistance in cancer cells." (PMID 37487022, 2023). "Therefore, MIR100HG regulates the extent of TGFβ signaling by promoting TGFβ1 autoinduction and secretion in carcinomas." (PMID 38042769, 2023). "The MIR100HG participates in multiple signaling pathways in diverse cancers." (PMID 36212400, 2022). "MIR100HG was originally discovered in a human transcriptome analysis, identified as a key role in neural stem cell neuronal differentiation and mesenchymal stem cell fate determination, and then discovered in diverse malignant tumors." (PMID 36212400, 2022). "These updates clarify our understanding of MIR100HG in cancers, which may pave the way for the application of MIR100HG-targeting approaches in future cancer diagnosis, prognosis, and therapy." (PMID 36212400, 2022). "Recent studies have begun to converge on miRNA-independent roles of MIR100HG in cancer." (PMID 35279145, 2022). "Knockdown of MIR100HG has an inhibitory effect on the tumorigenesis of cancers." (PMID 34381502, 2021). "Conversely, MIR100HG was significantly down‐regulated in RT‐4, UM‐UC‐3, T24 and 5637 cell lines compared with SV‐HUC‐1 cells and in cancer tissues compared with paired para‐cancerous tissues (P <.05)." (PMID 33797188, 2021). "Previous cancer studies have extensively described two lncRNAs in the shared ceRNA network, MAGI2-AS3, and MIR100HG." (PMID 34681112, 2021). "Querying the PanCancer Atlas expression data from ~10,000 patients, revealed that MIR100HG expression was significantly higher in the lung (where A549 cells belong) and prostate (where PC3U cells belong) carcinoma relative to other tumors." (PMID 33941855, 2021). "MIR100HG may promote the proliferation, migration, and invasion of cancer cells in LSCC by downregulating miR-204-5p, and MIR100HG may also have multiple downstream effectors in LSCC." (PMID 36212400, 2022). "Many of the top oncogene candidate lncRNAs (MIR100HG, LINC01268, FTX, etc.)were reported to promote cell growth or proliferation in different cancer types, suggesting that these lncRNAs may be involved at initial stages of tumorigenesis." (PMID 36359790, 2022). "Moreover, Mir100hg directly targets miR-15a-5p/miR-31-5p to enhance the glycolysis of non-stemness cancer cells, thereby enhancing their metastatic ability." (PMID 37735657, 2023). "MIR100HG was found significantly differentially expressed and down-regulated in CACX and CACX patients with pelvic lymph node metastasis (PLNM), and pathway analysis showed a significant correlation with the “cell growth and proliferation” and “cancer” phenotypes." (PMID 36212400, 2022).
MIR100HG also shares sentences with these, for which no sentence is quoted: cervical cancer (3 papers); hypospadias (2); lymph node metastasis (2); Alzheimer disease (1); brain tumor (1); breast tumors (1); cardiovascular disorder (1); cholangiocarcinoma (1); colon cancer (1); cutaneous melanoma (1); Fanconi anemia (1); glioma (1); head and neck carcinoma (1); liver cancer (1); malignant melanoma (1); metabolic disorders (1); nasopharyngeal carcinoma (1); neurological diseases (1); non-small cell lung carcinoma (1); pancreatic ductal adenocarcinoma (1); papillary thyroid cancer (1); rectum adenocarcinoma (1); squamous cell lung carcinoma (1); theileriasis (1).